MMAB (metabolism of cobalamin associated B)
Description:
Converts cob(I)alamin to adenosylcobalamin (adenosylcob(III)alamin), a coenzyme for methylmalonyl-CoA mutase, therefore participates in the final step of the vitamin B12 conversion. Generates adenosylcobalamin (AdoCbl) and directly delivers the cofactor to MUT in a transfer that is stimulated by ATP-binding to MMAB and gated by MMAA (Probable).
Synonyms: cblB; CFAP23; ATR; cob
Tractability: Small molecule: a structure with a bound ligand is known; it has a binding pocket of medium quality. PROTAC: its protein half-life has been measured.
Target class: Enzyme; Transferase
Gene: Protein-coding gene on chromosome 12 (109,553,715 to 109,573,580, reverse strand). Ensembl gene ENSG00000139428.
Subcellular location: Mitochondrion
Subcellular location (Human Protein Atlas): Mitochondria
Pathways (Reactome):
Disease: Defective MMAB causes MMA, cblB type
Metabolism: Cobalamin (Cbl) metabolism
Gene Ontology:
Molecular function: cobalamin binding; corrinoid adenosyltransferase activity; protein binding; transferase activity, transferring alkyl or aryl (other than methyl) groups
Biological process: cobalamin metabolic process
Cellular component: mitochondrion; mitochondrial matrix
Genetic constraint (gnomAD): Loss-of-function variants: 17 observed, 29.16 expected, observed/expected ratio (o/e) 0.58, 90% interval 0.4 to 0.87. The upper end of that interval is the gene's LOEUF score, 0.87, which puts it in group 3 of 6, group 1 being the genes least tolerant of losing a copy. Missense variants: 302 observed, 316.25 expected, observed/expected ratio (o/e) 0.95, 90% interval 0.87 to 1.05. Synonymous variants: 126 observed, 128.14 expected, observed/expected ratio (o/e) 0.98, 90% interval 0.85 to 1.14.
Gene-disease validity (ClinGen):
ClinGen rates the evidence that MMAB causes each of these diseases.
methylmalonic aciduria, cblB type (autosomal recessive): Definitive.
Homologues: Orthologues: chimpanzee MMAB (96% identical), macaque MMAB (92% identical), dog MMAB (85% identical), mouse Mmab (82% identical), rat Mmab (81% identical), guinea pig MMAB (80% identical), pig MMAB (74% identical), rabbit MMAB (72% identical), tropical clawed frog mmab (56% identical), zebrafish mmab (54% identical), Caenorhabditis elegans mmab-1 (35% identical).
Diseases named in the same sentence as MMAB in open-access papers:
MMAB is named in the same sentence as 24 diseases in open-access papers, as found by Europe PMC text mining. Sharing a sentence is not in itself a finding about the gene and the disease. The quoted sentences say what the papers report.
Methylmalonic aciduria (7 papers, 2015 to 2021). Increased concentration of methylmalonic acid in the urine. "From the top candidate genes, we were initially interested in the methylmalonic aciduria (cobalamin deficiency) cblB type (MMAB) gene." (PMID 34750386, 2021). "Methylmalonic aciduria (cobalamin deficiency) cblB type (MMAB) encodes a protein that catalyzes the final step in the conversion of vitamin B12 into adenosylcobalamin." (PMID 33152221, 2021). "Recent GWASes have found several novel loci at chromosome 12q24, including the mevalonate kinase (MVK) and methylmalonic aciduria (cobalamin deficiency) cblB type (MMAB) genes, both of which influence high-density lipoprotein cholesterol (HDL-C) levels." (PMID 29069827, 2017). "Little is known about the association of the mevalonate kinase (MVK), methylmalonic aciduria (cobalamin deficiency) cblB type (MMAB) single nucleotide polymorphisms (SNPs) and serum lipid levels." (PMID 29050287, 2017). "MMAB [methylmalonic aciduria (cobalamin deficiency) cblB type] encodes a protein that catalyzes the conversion of vitamin B12 into adenosylcobalamin, an active coenzyme form of B12." (PMID 26308950, 2015). "Methylmalonic aciduria cblB type (MMA cblB, OMIM #251110) is an inherited rare disease caused by mutations of the gene (MMAB) encoding for the enzyme ATP:cob(I)alamin adenosyltransferase (ATR, EC 2.5.1.17)." (PMID 32660097, 2020).
coronary artery disease (3 papers, 2012 to 2017). "Taken together, it is plausible that rs11067233 is associated with MMAB gene expression, which therefore could alter serum lipid concentrations, and accordingly modify the risk of coronary artery disease." (PMID 27716295, 2016).
dyslipidemia (3 papers, 2012 to 2017). "We systematically selected and genotyped 18 potentially functional polymorphisms in MVK, MMAB and KCTD10 by using the TaqMan OpenArray Genotyping System in a Chinese population including 399 dyslipidemia cases, 697 CHD cases and 465 controls." (PMID 27716295, 2016). "To determine whether polymorphisms in MVK, MMAB and KCTD10 are independently associated with the risk of dyslipidemia and CHD, we conducted a case–control study with 399 dyslipidemia cases and 465 controls in Han Chinese." (PMID 27716295, 2016). "Therefore, MVK, MMAB and KCTD10 genes may be candidates as susceptibility genes modulating HDL-C concentrations and then affect the risk of dyslipidemia and CHD." (PMID 27716295, 2016).
breast carcinoma (1 paper, 2013). "When examining ER- breast cancer, the burden of variants in MMAB remained one of the strongest associations (p = 2.0×10−5)." (PMID 23555315, 2013). "In breast cancer, the strongest associations included either SNPs in or gene burden scores for genes LDLRAD1, SLC19A1, FGFBP3, CASP5, MMAB, SLC16A6, and INS-IGF2." (PMID 23555315, 2013). "The MMAB gene is close to non-exonic SNPs that have been associated with HDL cholesterol and one of those GWAS SNPs (the intronic variant rs7134594) was among our top 100 single SNP associations with breast cancer." (PMID 23555315, 2013).
cblB-type methylmalonic aciduria (1 paper, 2022). "Pathogenic variants in MMAB cause cblB-type methylmalonic aciduria, an autosomal-recessive disorder of propionate metabolism." (PMID 34796408, 2022). "We identified bi-allelic disease-causing variants in MMAB in 97 individuals with cblB-type methylmalonic aciduria, including 33 different and 16 novel variants." (PMID 34796408, 2022).
deficiencies (1 paper, 2021). "MMAB has a key role in vitamin B12 metabolism, whereas vitamin B12 deficiencies are critically associated with myelin-related disorders, such as multiple sclerosis." (PMID 33911068, 2021).
depressive disorder (1 paper, 2012). A melancholy feeling of sadness and despair. "Among the cognate genes, six including ALG8, DGKE, GNA12, KLF11, LRPAP1, and MMAB are related to multiple genetic diseases such as depressive disorder and Type-II diabetes." (PMID 22348086, 2012).
Headache (1 paper, 2025). Cephalgia, or pain sensed in various parts of the head, not confined to the area of distribution of any nerve. "In contrast, the MMAB gene’s link to headache stems from metabolic dysfunction." (PMID 40943610, 2025). "For other associations, a prominent alternative was strong evidence for Hypothesis H3, exemplified by the link between an mQTL for MMAB and headache (PP.H3 = 0.994), which indicates the SMR signal is likely genuine but driven by two separate, closely linked variants." (PMID 40943610, 2025). "Similarly, genes identified for headache (e.g., ETFA, GRHPR, MMAB) and facial pain (e.g., FASN, SPHK2) also consistently showed protective trends at both the expression and protein levels." (PMID 40943610, 2025). "The gene set for headache (ETFA, GRHPR, MMAB) was enriched in two primary functional clusters: one centered on core mitochondrial energy pathways, including ‘oxoacid metabolism’; and another related to molecular binding functions, such as ‘nucleoside phosphate binding’." (PMID 40943610, 2025).
methylmalonic acidemia (1 paper, 2021). A genetically heterogenous inherited disorder characterized by abnormalities in the metabolism of lipids and proteins. "Isolated methylmalonic acidemia encompasses a heterogeneous group of inborn errors of metabolism with a wide spectrum of phenotypic severity, rate of disease progression, and long-term outcomes, especially for patients with the severe MMUT or MMAB enzymatic defects." (PMID 33820958, 2021).
metabolic disease (1 paper, 2023). A congenital disorder (due to inherited enzyme abnormality) or acquired (due to failure of a metabolically important organ) disorder resulting from an abnormal metabolic process. "In the present study, we identified a single nucleotide variant in exon 7 of the MMAB gene, the NM_052845.4 (MMAB):c.557G > A, p.Arg186Gln, in WES data analysis of a neonate who died from an unknown metabolic disease." (PMID 37248539, 2023).
MMAB also shares sentences with these, for which no sentence is quoted: cobalamin deficiency (5 papers); Alzheimer disease (2); autism (1); cancer (1); congenital disorder of glycosylation (1); genetic diseases (1); homocystinuria (1); insomnia (1); ischemic stroke (1); major depressive disorder (1); mitochondrial disease (1); Obesity (1); schizophrenia (1); Type-II diabetes (1).